CDH12 (cadherin 12)
Diseases named in the same sentence as CDH12 in open-access papers (continued):
Sharing a sentence is not in itself a finding about the gene and the disease.
glioma (1 paper, 2022). A benign or malignant brain and spinal cord tumor that arises from glial cells (astrocytes, oligodendrocytes, ependymal cells). "Moreover, the EGFR and MUC16 mutations were also significantly enriched in cases within high‐risk group, while mutations in CIC, NOTCH1, ATRX, and CDH12 occurred more frequently in the low‐risk group, these characteristics are consistent with the update WHO CNS5 classification of glioma." (PMID 35985661, 2022).
myopia (1 paper, 2010). "Six candidate genes CDH6, CDH10, CDH12, PDZD2, GOLPH3, and ZFR at this high myopia locus were selected on the basis of their function to screen for gene mutations by re-sequencing." (PMID 21042559, 2010).
Obstructive Uropathies (1 paper, 2021). "The role of CDH12 in monocyte infiltration and the development of kidney injury in PUV, and the predictive value of rs6874819 for the prognosis of individual PUV patients are important future research topics, as is the generalizability of our findings to other forms of obstructive uropathy." (PMID 34337522, 2021).
thyroid cancer (1 paper, 2024). "Schematic summary of FTO-IGF2BP2 axis in modulation of CDH12 mRNA m6A and upregulation of CDH12 expression in the invasion and metastasis of thyroid carcinoma." (PMID 39379360, 2024). "CDH12 promotes invasion and metastasis through the EMT pathway in thyroid cancer, both in vivo and in vitro." (PMID 39379360, 2024).
cancer (16 papers, 2013 to 2024). A tumor composed of atypical neoplastic, often pleomorphic cells that invade other tissues. "CDH12 has been associated with angiogenesis and progression of several types of cancers." (PMID 35754128, 2022). "CDH12 has been reported to promote proliferation, migration, invasion, adhesion, and angiogenesis, suggesting that it may be an oncogene, diagnostic, and prognostic marker for several cancers." (PMID 38200081, 2024). "This is consistent with our finding that elevated CDH12 expression drives enhanced malignancy in anastatic cancer cells after exposure to chemotherapeutic drugs." (PMID 37355711, 2023). "For example, the cadherin-12 (CDH12) gene has been shown to increase cancer cell migration, invasion and progression via promoting EMT by targeting the transcriptional factor Snail." (PMID 36551919, 2022). "We observed many significantly enriched interactions between the CDH12 population and fibroblasts, with the most notable being TGFBR1, CD44, and several integrins because of their involvement in cancer-associated fibroblast (CAF) activation." (PMID 34385456, 2021). "Studies have confirmed that CDH12 is essential for the progression of multiple cancers, such as salivary adenoid cystic carcinoma, colorectal cancer, and non-small cell lung cancer." (PMID 34820384, 2021). "Only a few studies have focused on the function of CDH12, such as promoting migration and invasion in cancers." (PMID 34820384, 2021). "CDH12 is able to increase cancer cell migration and invasion via promoting EMT by targeting transcriptional factor Snail." (PMID 26762412, 2016). "We identified CREB as the mediator for cancer cell proliferation and migration driven by CDH12." (PMID 37355711, 2023). "However, some amplified genes in treated HEK293T (e.g., BMP7, MRGBP, CDH12) are associated with EMT in PDAC and other cancer types." (PMID 36289850, 2022). "CDH12 belongs to cadherin family which acts as an important regulator of cancer cell migration." (PMID 26762412, 2016). "Thus it is possible that the CDH18 gene and other nearby genes identified in cohort (including CTNND2, CDH12 and MYO10) play a mechanistic role in the observed connection between MetS and cancer risk." (PMID 23628382, 2013). "Consequently, the decreased expression of CDH12, along with reduced adhesive molecules, may contribute to a more aggressive and metastatic phenotype in cancer cells." (PMID 38003292, 2023). "However, the impact of CDH12 on cancer didn’t attract more attention until recent years." (PMID 24237488, 2013). "A new method for the determination of cadherin 12 (CDH12)—an adhesive protein that has a significant impact on the development, growth, and movement of cancer cells—was developed and validated." (PMID 38069216, 2023). "Western blot was used to detect the CDH12 expression in CRC cell lines, including the non-cancer cell line NCM460." (PMID 24237488, 2013). "CDH12 has not been described in relation to kidney development before, but it is involved in the progression of several cancers." (PMID 34337522, 2021). "SW620 cells expressing low CDH12 levels had a typical epithelium-like appearance not the mesenchymal phenotype which favors the metastasis of cancer cells." (PMID 26762412, 2016). "Considering the important role of EMT in cancer cell invasion into vessels, during EMT, a tumor cell with epithelial characteristic transitions to tumor cell with mesenchymal characteristics through modulation of cell polarity and adhesion, we investigated the influence of CDH12 in EMT markers." (PMID 26762412, 2016).
tumor (11 papers, 2013 to 2024). "High expression of CDH12 was associated with tumor invasion depth and predicts poor prognosis of CRC patients." (PMID 26762412, 2016). "The loss or downregulation of CDH12 can disrupt the adhesive interactions between cells, leading to a decreased cohesive behavior within the primary tumor and facilitating the detachment of tumor cells from the primary site." (PMID 38003292, 2023). "Tumor cells were found to express Cadherin 12 (CDH12), which was predominantly found in the basal/squamous, luminal-infiltrating and neuroendocrine-like subtypes, and was significantly absent in the luminal papillary and luminal indeterminate subtypes." (PMID 39559360, 2024). "Conceivably, transformation at this juncture would lead to tumor development with an enrichment of the CDH12 population." (PMID 34385456, 2021). "Compared with control groups, the size and weight of tumor nodules were markedly suppressed in CDH12 downregulation group (SW620/shCDH12)." (PMID 26762412, 2016). "To elucidate function of CDH12 in tumor development in vivo, we have chosen nude mice to perform animal experiments." (PMID 26762412, 2016). "Simultaneously, adhesion assay that cells numbers attached to the HUVEC monolayer in shCDH12 group were less than the control group, revealed the importance of CDH12 in the adhesion of tumor cells to endothelial cell." (PMID 24237488, 2013). "In view of its role in tumor life processes, migration, and angiogenesis CDH12 is a potential marker for the characterization of the patient’s condition, and CDH12 determinations have been carried out to date using several immunochemical methods (including ELISA) and semiquantitative Western blot." (PMID 38069216, 2023). "We then assessed the effect of CDH12 knockdown on in vivo tumor growth and metastasis." (PMID 37355711, 2023). "Given our observation that chemotherapy substantially alters tumor composition by enriching for the CDH12 population, we split the IMvigor210 cohort into samples originating from bladder that were taken pre-chemotherapy or post-chemotherapy (see methods for cohort selection details)." (PMID 34385456, 2021). "Statistical analyses were used to analyze relationship between CDH12 and tumor features." (PMID 26762412, 2016). "In statistical analysis of clinical materials, we found that CDH12 high expression was associated with invasion depth of tumor tissue and lymph node lesions, independent of age, gender, tumor site, tumor histology, and tumor size." (PMID 26762412, 2016). "Similarly, in CDH12 overexpression group (HCT116/CDH12), size and weight of tumor formed in nude mice were significantly higher than that in control groups." (PMID 26762412, 2016). "We found that expression of CDH12 in tumor tissue was higher than in adjacent normal tissue." (PMID 26762412, 2016). "After being washed with PBS, the number of SW1116 cells adhered to the HUVEC monolayer in the shCDH12 group was less than the shNC group.These suggest that CDH12 is an essential adhesion molecule not only to tumor cells junctions but also to the adhesion between tumor cells and endothelial cells." (PMID 24237488, 2013). "Considering the importance of angiogenesis in tumor metastasis and the contribution of CDH12 in tumor cell migration, invasion and cell cycle, CDH12 maybe a potential target to supervise tumor cell malignant metastasis." (PMID 24237488, 2013). "Collectively, the result demonstrates that CDH12 may promote tumor cells to attach to the vascular enthelial cells during tumor metastasis." (PMID 24237488, 2013). "CDH12 may also promote tumor metastasis through this switching mechanism." (PMID 24237488, 2013). "Furthermore, we showed down-regulation of CDH12 can obviously inhibit the process of angiogenesis, implying that CDH12 may play an important role in tumor metastasis." (PMID 24237488, 2013).
tumor (continued). "To validate that CDH12 epithelial cells co-localize with T-cells at the single-cell level, we designed and executed a 35-plex IHC panel using the Co-detection by indexing (CODEX) platform on tumor tissue microarrays of the same tumor cohort 40,41." (PMID 34385456, 2021). "Statistical analysis of clinical cases revealed that the positive rate of CDH12 was higher in the CRC tumor tissues compared with the adjacent non-tumor tissues." (PMID 24237488, 2013). "Cell adhesion assay and cell aggregation assay presented that tumor cells tend to disperse with the lack of CDH12." (PMID 24237488, 2013).
CDH12 also shares sentences with these, for which no sentence is quoted: depression (2 papers); lymph node metastasis (2); Ovarian cyst (2); atherosclerosis (1); autism spectrum disorder (1); glioblastoma (1); kidney injury (1); microcephaly (1); neurodegenerative disease (1); posterior urethral valve (1); psoriasis (1); psychiatric disorder (1).